MTOR (mechanistic target of rapamycin kinase)
Diseases named in the same sentence as MTOR in open-access papers (continued):
Sharing a sentence is not in itself a finding about the gene and the disease.
epilepsy (continued). "Here, we investigated whether constitutive mTOR hyperactivation in the hippocampus is associated with altered voltage-gated ion channel expression in the neuronal subset-specific Pten knockout (NS-Pten KO) mouse model of CD with epilepsy." (PMID 29476105, 2018). "However, both brain injury and mTOR are linked to epilepsy, raising the possibility that IGF-1 may be epileptogenic." (PMID 27561791, 2016). "RNA sequencing revealed that differentially expressed genes in ETs were enriched in the PI3K‐AKT pathway, and the PI3K/AKT/mTOR pathway is known to be the pathological basis of TSC‐related epilepsy." (PMID 41090516, 2026). "These insights enhance the understanding of mTOR pathway involvement in TSC‐related epilepsy and underscore the potential of targeting mTORC1, as well as epigenetic factors like NEAT1, for more effective therapeutic strategies." (PMID 41090516, 2026). "Meanwhile, prior studies have shown that GV14 stimulation modulates the AKT/mTOR signaling pathway to treat epilepsy and promotes hippocampal neuron autophagy during epileptic seizures." (PMID 41143153, 2025). "Somatic variants in genes within this pathway, such as MTOR, TSC1/2, DEPDC5, and AKT3 have been frequently identified in patients with epilepsy-associated MCD." (PMID 39859528, 2025). "mTOR pathway activation occurs in neurons and glia in epilepsy surgical pathologies in addition to FCD II, as identified by downstream pS6 protein." (PMID 40299318, 2025). "Disruption of mTOR signaling due to variants in its repressors such as TSC1, TSC2, DEPDC5, PTEN or in its activators such as RHEB, and MTOR lead to a set of disorders characterized by early onset and often drug-resistant epilepsies called mTORopathies." (PMID 40792287, 2025). "While epilepsy is characterized by abnormal neuronal electrical activity, mTOR overactivation contributes to this through multiple mechanisms." (PMID 39865817, 2025). "We found that genes of the mTOR pathway (RPS6, RHEB, EIF4E) were highly expressed in the PY2 pyramidal neurons, consistent with the activation of the mTOR pathway in histopathological neurons in the epileptic focus of drug-resistant epilepsy." (PMID 40026248, 2025). "This complexity, coupled with mTOR’s critical involvement in various diseases such as cancer and epilepsy, underscores the need for alternative therapeutic approaches, including gene therapy." (PMID 40358185, 2025). "Mycophenolate has also been shown to inhibit the phosphatidylinositol 3-kinase (PI3K)-Akt-mammalian target of rapamycin (mTOR) pathway, an important downstream signaling pathway of orbital fibroblasts, in a rat model of epilepsy." (PMID 40145088, 2025). "These events promote maladaptive synaptic remodeling and impair early functional connectivity, an effect that also appears in mosaic mTOR pathway disorders such as epidermal nevus syndromes, which frequently present with early-onset epilepsy and ISs." (PMID 41470225, 2025). "Beyond TSC, mTOR inhibitors are also under investigation for mTOR-related epilepsies such as FCD, another mTORopathy, where early data suggest improved seizure control and slowed disease progression." (PMID 41301687, 2025). "Several cell signaling pathways play critical roles in epilepsies, with the mechanistic target of rapamycin (mTOR) pathway being the most prominent." (PMID 40310132, 2025). "Our findings confirm that variants in mTOR pathway genes (not only in DEPDC5) are present in patients with ICA and underline the potential risk of sudden unexpected death in epilepsy." (PMID 40971258, 2025). "IPA of differentially methylated transcripts from the combined epilepsy sample group highlighted autophagic pathways, mTOR signalling, and metabolism as pathways likely to be affected by disrupted methylation patterns in epilepsy." (PMID 40693462, 2025). "Animal models have been essential for understanding the link between hyperactivated mTOR and epilepsy in patients with TSC." (PMID 41255962, 2025).
epilepsy (continued). "These rapalogs neutralize the hyperactive mTOR pathway in several neurodevelopmental disorders, such as epilepsy." (PMID 41286527, 2025). "These mechanistic insights have enabled the successful clinical translation of mTOR inhibitors (rapamycin, everolimus) in TSC-associated epilepsy, demonstrating significant seizure frequency reduction (50% responder rate) and cognitive improvement." (PMID 40979205, 2025). "Previous studies have supported glial dysfunction in the pathophysiology of mTOR-related epilepsy in both mouse models and clinical studies of TSC." (PMID 40996830, 2025). "In summary, our work positions mTOR as one potential modulator of seizure severity in hcfc1a-deficient zebrafish, offering a mechanistic bridge between HCFC1 dysfunction and epilepsy." (PMID 41562862, 2025). "Mechanistically, the DEPDC5 gene contributes to epilepsy development by regulating the mTOR pathway." (PMID 41141423, 2025). "In summary, the role of mTOR in tau phosphorylation in epilepsy requires further experimental study, including at the single‐cell level." (PMID 40299318, 2025). "Given the wide range of physiological functions of mTOR, inhibition of its effective but relatively simple functional downstream molecules is a promising target for the development of drugs for epilepsy." (PMID 37736829, 2024). "In animal models of epilepsy and human tissue samples removed from epilepsy patients showed evidence of overactive mTOR signaling pathways in both hereditary and acquired epilepsies." (PMID 39845785, 2024). "Elevated mTOR activity has been consistently associated with neurological disorders relating to ASD, epilepsy, and neurodegenerative disorders." (PMID 39335388, 2024). "Reducing tau in epilepsy mouse models (particularly in excitatory neurons) is therapeutic: it decreases mortality, seizures, the overactivation of the mTOR signalling pathway, and ameliorates abnormalities in learning and memory." (PMID 38289539, 2024). "The diminished regulatory function of TSC1 results in the activation of the mTOR pathway, which subsequently leads to tumorigenesis and epilepsy." (PMID 40217423, 2024). "Loss of the TSC gene in mouse models results in seizures and epilepsy that can be attenuated with the mTOR inhibitor, rapamycin." (PMID 38390593, 2024). "In this review, we focus on describing the role of mTOR and the related pathways in depression, schizophrenia, and epilepsy and summarize specific antipsychotics that exert their pharmacologic effects via the activity of the mTOR signaling pathway." (PMID 38365306, 2024). "Specifically, the activity of the PI3K/Akt/mTOR signaling pathway is upregulated in the temporal and frontal cortices of patients with epilepsy or recurrent seizures." (PMID 38365306, 2024). "The efficacy, tolerability, and safety of other forms of anti-seizure treatment, such as the mammalian target of rapamycin (mTOR) inhibitors, like rapamycin (Sirolimus), have been researched in other pediatric seizure disorders, as well as in SWS." (PMID 39598668, 2024). "The mTOR-inhibitor everolimus is a precision drug with antiepileptogenic properties approved for treatment of epilepsy in persons with tuberous sclerosis complex (TSC) in combination with other antiseizure medications (ASMs)." (PMID 39121325, 2024). "Using mTOR as a target, the novel therapeutic agent everolimus improves the understanding of the pharmacological framework of epilepsy isolated from Auvin and Baulac (2023)." (PMID 38962319, 2024). "Overall, these results suggest a complicated, developmentally regulated role for 4E-BPs in mTOR-induced epilepsy." (PMID 37680968, 2023). "Taken together, this highlights the importance neuroinflammatory-related pathways in mTOR-related signaling in general, potentially implicating it in epilepsy pathogenesis as well." (PMID 36675042, 2023). "It has been shown that the ketogenic diet and its substrates β‐hydroxybutyrate attenuate astrogliosis and mTOR activation in mice with epilepsy." (PMID 37737447, 2023).
epilepsy (continued). "The regulatory effect of mTOR on neuronal autophagy has also been validated in animal and cellular models of epilepsy." (PMID 37221133, 2023). "The mTOR pathway functions as a vital mediator in epilepsy development through diverse mechanisms, indicating that the it has great potential as an effective target for epilepsy therapy." (PMID 37221133, 2023). "Apparent overactivation of mTOR signalling is prevalent in multiple types of epilepsy, including those resulting from genetic defects or acquired trauma." (PMID 38067243, 2023). "Dysregulation of the mammalian target of the rapamycin (mTOR) pathway is thought to play an important role in the onset and progression of some epilepsies." (PMID 37221133, 2023). "Modulating miR-10a levels affected cytokine secretion and the PI3K/Akt/mTOR pathway, suggesting its potential as a therapeutic target for epilepsy." (PMID 37653173, 2023). "Various studies have also evaluated the inhibitory effect of a KD on mTOR activity in rodent models of mitochondrial disease, epilepsy, and longevity." (PMID 37076659, 2023). "Regulation of the mTOR pathway provides a potential strategy for the treatment and prevention of epilepsy." (PMID 37221133, 2023). "In epilepsies caused by alterations in mTOR pathway genes, such as DEPDC5, TSC1, or TSC2, the drug rapamycin can be used to manage symptoms as it inhibits mTOR pathway." (PMID 37834053, 2023). "This interplay sheds light on the multifaceted mechanisms through which epilepsy shapes neurological processes and underscores the significance of mTOR regulation in these contexts." (PMID 40217521, 2023). "It has been shown that rapamycin and other mTOR inhibitors attenuate T cell migration and development of neuroinflammation which trigger epilepsy and SE in different autoimmune disorders like new-onset refractory SE and encephalitis-induced seizure." (PMID 37880579, 2023). "Expression levels of miR-21-5p and mTOR have been found to be elevated in rats across different phases of epilepsy, while PTEN is down-regulated." (PMID 37653173, 2023). "The epileptogenic action of the d-2-HG oncometabolite and its ability to activate the mTOR pathway open up the potential use of mTOR inhibitors as rapamycin, everolimus, and temserolimus for patients with IDH1 mutated tumors and drug refractory epilepsy." (PMID 37071297, 2023). "Accordingly, administration of the potent mTOR inhibitor, rapamycin, has been reported to prevent epilepsy, disrupt tumour metabolism as well as impair mitochondrial disease progression in various animal models." (PMID 37076659, 2023). "Mutations in different regions of the mTOR pathway can lead to the development of epilepsy, and taking mTOR inhibitors reduces the number of seizures." (PMID 38067243, 2023). "Even so, recent studies have revealed multiple ways in which the mTOR pathway triggers or exacerbates epilepsy." (PMID 37221133, 2023). "Background: mTOR inhibitors are a novel pharmacotherapy recommended for subependymal giant astrocytomas, refractory epilepsy, and the treatment of the other clinical manifestations of tuberous sclerosis complex (TSC)." (PMID 36615165, 2023). "Children who started using the mTOR inhibitor after 2 to 3 months from the beginning of epilepsy had good control of symptoms, whereas those who started after 4 to 8 months did not." (PMID 36863402, 2023). "Previous research found electroacupuncture treatment promotes autophagy during epilepsy onset by significantly downregulating the AKT/mTOR signaling pathway, which is consistent with our research." (PMID 38020614, 2023). "In a rat model of pilocarpine‐induced epilepsy, activation of the mTOR signaling pathway inhibits neuronal autophagy and avoids neuronal apoptosis, which can prevent acute epilepsy." (PMID 37221133, 2023). "Accordingly, this review focuses on the latest findings of the mTOR signaling pathway and rapamycin in the treatment of epilepsy." (PMID 37221133, 2023).
epilepsy (continued). "Another important mTOR regulator involved in epilepsy is dual specificity tyrosine-phosphorylation-regulated kinase 1A (DYRK1A), an inhibitor of mTORC1." (PMID 36982355, 2023). "Variations in the mTOR pathway genes are found to be associated with ASD and strongly comorbid with epilepsy." (PMID 36819340, 2023). "This review summarizes the role of the mTOR signaling pathway in the pathogenesis of epilepsy and the prospects for the use of mTOR inhibitors." (PMID 37221133, 2023). "The effectiveness of mTOR inhibitors in modulating aberrant mTOR signaling before seizures and ameliorating epilepsy in infants with TSC remains to be elucidated." (PMID 37221133, 2023). "A total of 33 children underwent preoperative genetic whole‐exome testing, and 4 of them had pathogenic genes related to epilepsy, including CACNA1A, CREBBP, MTOR, and NPRL2." (PMID 37786975, 2023). "At the molecular level, hyperactivation of the mammalian target of rapamycin (mTOR) signaling pathway has been observed in several models of epilepsy and inhibition of mTOR reduces seizure activity." (PMID 38130682, 2023). "These verdicts propose that metformin has anti‐seizure activity by activating AMPK signalling and inhibiting mTOR pathways which are dysregulated in epilepsy." (PMID 37737447, 2023). "To examine the roles of the mTOR complexes in epilepsy, we employed kainic acid (KA), a well-studied model of pharmacoresistant hippocampal epileptogenesis." (PMID 37963879, 2023). "In conclusion, data from animal experiments and clinical studies confirm that mTOR inhibitors show great potential as new drugs for epilepsy treatment." (PMID 37221133, 2023). "Here, we discuss recent advances and current challenges in developing experimental models of mTOR-dependent epilepsy and other related mTORopathies, including using the zebrafish (Danio rerio), as well as outline future directions of research in this field." (PMID 36675042, 2023). "Our findings showed abundant p‐tau (Ser202/Thr205)‐related NT and NFT pathology, with variable levels of p‐tau at two phosphorylation sites (Thr205 and Thr181), Aβ deposits and mTOR activation in brain biopsies from drug‐resistant epilepsy cases." (PMID 37052232, 2023). "Data from other rodent models of hyperactive mTOR induced epilepsy and ASD‐like behavior suggest that the earlier treatment can begin, the more likely ASD‐like behaviors can be affected." (PMID 37376966, 2023). "Mutations in the mTOR-inhibiting (e.g., tuberous sclerosis TSC1, TSC2 and GATOR1 complex) genes are particularly strongly linked to epilepsy." (PMID 36982355, 2023). "Although one mTOR blocker, everolimus, is approved for the treatment of epilepsy in one of these disorders, tuberous sclerosis complex, this drug has severe side effects and seizures remain in most patients." (PMID 37620147, 2023). "Further explorations are needed to evaluate the therapeutic efficacy and application value of mTOR inhibitors in epilepsy." (PMID 37221133, 2023). "Many animal experiments have demonstrated that activation of the mTOR pathway is closely related to the occurrence of epilepsy." (PMID 37221133, 2023). "In this paper, we describe six cases of drug‐resistant epilepsy due to FCDII and mTOR pathway germline gene mutations." (PMID 37574648, 2023). "Because microtubular organization plays an important role in both neurons and its synapses, its disruption by CLIP-170 is in line with the link between aberrant mTOR pathway and epilepsy." (PMID 36675042, 2023). "The mTOR signaling pathway is a driver of epilepsy in tuberous sclerosis complex and focal cortical dysplasias [14••]." (PMID 37071297, 2023). "Metformin has anti‐seizure activity by triggering adenosine monophosphate‐activated protein kinase (AMPK) signalling and inhibiting the mechanistic target of rapamycin (mTOR) pathways which are dysregulated in epilepsy." (PMID 37737447, 2023).
epilepsy (continued). "According to Vieira’s statement in 2021, dysregulation of the PI3K/ Akt/mTOR pathway and consequently different pattern of inflammatory cytokine production occurs in neurodegenerative diseases such as epilepsy." (PMID 37605727, 2023). "Although an mTOR analog is approved for the treatment of epilepsy in one of these disorders, it has limited efficacy and is associated with a wide range of side effects." (PMID 37620147, 2023). "In 2017, everolimus was approved by FDA and EMA for the treatment of drug-resistant epilepsy associated with TSC and became the main mTOR inhibitor used in this indication." (PMID 35572924, 2022). "Meanwhile, accumulating evidence has revealed that non-coding RNAs (ncRNAs) interfering with mTOR signaling are involved in neuroinflammation and therefore articipate in the development and progression of epilepsy." (PMID 35898503, 2022). "In summary, the results of our study point to pioglitazone as a promising candidate in treating epilepsy through antiepileptogenic mechanisms affecting the mTOR pathway." (PMID 36145334, 2022). "Recent evidence supports the solid correction between mTOR-dependent autophagy and multiple seizure models and epilepsies." (PMID 36078029, 2022). "Series of studies have demonstrated that miRNAs mediate neuroinflammation and play a crucial role in the development and progression of epilepsy via mTOR pathway." (PMID 35898503, 2022). "These two studies demonstrate that the blockage of the autophagy flux and the accumulation of aberrant autophagic structures occur along with lower autophagy activity in epilepsy, but with normal mTOR signaling." (PMID 36078029, 2022). "Although mTOR-inhibitors show definite efficacy in epilepsy, their effectiveness in TAND remains controversial." (PMID 35359647, 2022). "Expression levels of miR-21-5p and mTOR have been shown to be increased in rats during acute, latent, and chronic phases of epilepsy parallel with down-regulation of PTEN." (PMID 35088379, 2022). "The paradoxical increase of autophagy markers in the context of autophagy disruption is the case for mTOR-independent autophagy inhibition, which should also be taken into account when monitoring the autophagic status of epilepsy." (PMID 36078029, 2022). "In this study, five subjects with TSC (26%) were treated with an mTOR-inhibitor (four had refractory epilepsy, one was the treatment of SEGA)." (PMID 35359647, 2022). "Neuroinflammation acting as the inflammatory response to epileptic seizures is characterized by aberrant regulation of inflammatory cells and molecules, and has been regarded as a key process in epilepsy where mTOR signaling serves as a pivotal modulator." (PMID 35898503, 2022). "This ‘mTOR’ pathway, is appreciated for its role in epilepsy, and the mTOR protein complex specifically has been the target of anti-epilepsy or anti-seizure drugs, with many mTOR inhibitors effectively preventing seizures." (PMID 36059958, 2022). "Hyperactivation of the mTOR pathway contributes to drug-resistant epilepsy that renders it a target for intervention." (PMID 36286014, 2022). "CLOCK and BMAL1 are also involved in the regulation of the mTOR pathways consistent with the notion that mTOR and the circadian system interact to promote epilepsy." (PMID 35487880, 2022). "Preclinical studies are needed to understand the pathophysiology of epilepsy in GNAO1 and GNB1 deficiency and to clarify the role of the mTOR signaling pathway activation." (PMID 36003298, 2022). "Inhibition of mTOR activity is capable of preventing epilepsy-induced neuronal alterations and the development of epilepsy." (PMID 36078029, 2022). "The nuclear paraspeckle assembly transcript 1 (NEAT1) has been demonstrated to regulate both neural activity and inflammation though interacting with mTOR pathway in epilepsy." (PMID 35898503, 2022). "Multiple studies in the disease models we reviewed found changes associated with IGF-1, mTOR, or the related AMPK pathway in AD, PD, MS and epilepsy." (PMID 36501116, 2022).